IL11 (interleukin 11)
Diseases named in the same sentence as IL11 in open-access papers (continued):
Sharing a sentence is not in itself a finding about the gene and the disease.
keloid (1 paper, 2025). An irregularly shaped, elevated mark on the skin caused by deposits of excessive amounts of collagen during wound healing. "IL-6 and IL-11, two closely related gp130-family cytokines, have emerged as key mediators at the interface of inflammation and fibrosis, providing a mechanistic link that is highly relevant to keloid pathogenesis." (PMID 41562114, 2025).
kidney injury (1 paper, 2022). Trauma to the kidney. "Following acute kidney injury, Il11 mRNA and IL11 protein levels were increased in the kidneys of wild-type (WT) mice as compared to WT controls." (PMID 36470928, 2022). "Thus, our data suggest that anti-IL11 provides protection against chronic consequences of AKI even when administered three days after induction of kidney injury." (PMID 36470928, 2022).
kidney stone (1 paper, 2023). "By comparing kidney stones groups with normal groups, Cluster 9 emerged as the most strongly associated with IL11." (PMID 37480086, 2023). "This was confirmed by analysis of three independent datasets, indicating that IL11 could potentially serve as a diagnostic biomarker for kidney stones in diabetic patients." (PMID 37480086, 2023). "Further investigation is necessary to validate both the exact involvement of IL11 in the formation of kidney stones, as well as to determine the manner in which sex-related variances in IL11 impact the development of kidney stones." (PMID 37480086, 2023). "Subsequent analysis of the expression profiles of IL11 in a patient cohort revealed that its expression levels were markedly raised in both the kidney stones and diabetic groups as compared to the control group." (PMID 37480086, 2023). "However, the precise role of IL11 in kidney stone formation and how sex differences in IL11 affect kidney stones development require further research for confirmation." (PMID 37480086, 2023). "In this current research, IL11 expression was considerably increased in male patients but not in female patients, highlighting the potential sex-specific effects of IL11 in the diagnosis and treatment of kidney stones in diabetic patients." (PMID 37480086, 2023). "The diagnostic potential of IL11 was further evaluated using ROC curves based on the GSE73680 and GSE41762 datasets, which suggest that IL11 could potentially act as a diagnostic biomarker for kidney stones in diabetic patients." (PMID 37480086, 2023).
Legionella pneumonia (1 paper, 2011). "Further studies examining other factors, such as IL-11, GM-CSF and KGF, may be important to correctly characterize the roles and significance of cytokines and growth factors in Legionella pneumonia under hyperoxia." (PMID 21470397, 2011).
leiomyoma (1 paper, 2021). A well-circumscribed benign smooth muscle neoplasm characterized by the presence of spindle cells with cigar-shaped nuclei, interlacing fascicles, and a whorled pattern. "Major cytokines, namely the expression of interleukin 1 (IL1), 6 (IL6), 11 (IL11), 13 (IL13), 15 (IL15), 33 (IL33), tumor necrosis factor α (TNFα), and the granulocyte-macrophage colony-stimulating factor, have been implicated to leiomyoma pathophysiology." (PMID 34442017, 2021). "Numerous studies described leiomyoma cells exhibiting a significantly greater expression of IL1, IL4, IL5, IL6, IL10, IL11, IL13, and IL15." (PMID 34442017, 2021).
liver cirrhosis (1 paper, 2025). "Our study identified a significant positive correlation between MCM7 and IL11 expression in patients with liver cirrhosis." (PMID 40789837, 2025). "Furthermore, in liver cirrhosis patients, a positive correlation was observed between the expression of MCM7 or SHCBP1 mRNA and increased IL11 expression." (PMID 40789837, 2025).
macular pucker (1 paper, 2024). "To better understand the role of IL-11 in disease pathogenesis, we compared the concentrations of IL-11 in human vitreous and plasma samples from 15 PDR patients to those from 15 control patients with macular pucker." (PMID 39294742, 2024).
meningeal TB (1 paper, 2012). "Among potential clinical signatures reported are CXCL9, CXCL10, CCL1, and IL11, as their expression levels could differentiate some kinds of clinical manifestations such as latent TB, pulmonary, and meningeal TB." (PMID 22675550, 2012).
metastatic cancer (1 paper, 2023). A carcinoma which has spread from the original site of growth to another anatomic site. "Previous findings showed that Parathyroid hormone-related protein (PTHrP), receptor activator of nuclear factor-κB ligand (RANKL) and interleukin (IL)-11, IL-8, IL-6, etc, produced by metastatic cancer cells, are involved in osteolytic bone metastases." (PMID 37333824, 2023).
myocardial ischemia (1 paper, 2023). A disorder of cardiac function caused by insufficient blood flow to the muscle tissue of the heart. "Initial reports on the role of IL11 in the myocardium described cardioprotective, anti-fibrotic, and anti-inflammatory effects of recombinant human IL11 (rhIL11) in the setting of myocardial ischemia in mice." (PMID 37629170, 2023).
necrotizing enterocolitis (1 paper, 2019). Necrotizing enterocolitis (NEC) is a devastating disease that affects mostly the intestine of premature infants. "Studies have shown that recombinant human IL-11 can reduce the incidence of extensive necrotizing enterocolitis (NEC) in infants." (PMID 31864417, 2019).
osteitis (1 paper, 2021). "Higher expression levels of inflammatory cytokines, such as IL-6, IL-11, and TNF-α, were identified more in the bone tissue obtained from CRS patients with osteitis than in those without osteitis." (PMID 33477617, 2021).
ovarian hyperstimulation syndrome (1 paper, 2023). A complication of ovulation induction in infertility treatment. "Moreover, clinical studies have demonstrated that concentrations of IL-11 in follicular fluid increase in patients with polycystic ovary syndrome (PCOS) and ovarian hyperstimulation syndrome (OHSS)." (PMID 36831340, 2023).
pancreatitis (1 paper, 2022). Inflammation of the pancreas. "We investigate whether autocrine IL11 signalling in PSCs is required for PSC activation downstream of various profibrotic cytokines implicated in pancreatitis." (PMID 35408908, 2022). "In contrast to our findings, an early study showed that administration of recombinant human IL11 reduced disease severity in the caerulein-induced mouse model of pancreatitis." (PMID 35408908, 2022). "In pancreatitis, IL11 expression was highest in cells within regions of interlobular fibrosis and in acinar cells." (PMID 35408908, 2022). "This is the first description of IL11-mediated activation of PSCs, and the data suggest IL11 as a stromal therapeutic target in pancreatitis." (PMID 35408908, 2022). "Earlier studies have shown that IL11 is elevated in the serum of patients with severe pancreatitis." (PMID 35408908, 2022). "We end by suggesting that therapies targeting IL11 signalling may be considered as a therapeutic approach for patients with pancreatitis." (PMID 35408908, 2022). "To determine the role of IL11 in PSC activation and pancreatitis in vivo, we used the established pancreatic duct ligation (PDL) mouse model of pancreatitis." (PMID 35408908, 2022). "Pancreatitis factors, including TGFβ, CTGF and PDGF, induced IL11 secretion from PSCs and a neutralising IL11RA antibody prevented PSC activation by these stimuli." (PMID 35408908, 2022). "Given the similarities between the HSCs and PSCs and the established role of IL11 as a pro-fibrotic factor in several other tissues, we hypothesised that IL11 could be important for PSC activation and pancreatitis." (PMID 35408908, 2022). "Although we did not investigate the specific role of IL11 in the immune response in pancreatitis, we found that blocking IL11 signalling had anti-inflammatory effects and reduced IL6, IL1β and TNFα protein levels as well as diminishing NF-κB and STAT3 activation." (PMID 35408908, 2022). "The role of IL11 in PSC biology and in pancreatitis remains unclear." (PMID 35408908, 2022). "Our data reveal that multiple pancreatitis factors induce IL11 secretion from PSCs and that autocrine IL11 activity is important for PSC activation, which suggests a non-redundant role for IL11 in pancreatitis." (PMID 35408908, 2022).
Pancytopenia (1 paper, 2025). An abnormal reduction in numbers of all blood cell types (red blood cells, white blood cells, and platelets). "It has been previously shown that G-CSF, granulocyte-monocyte colony-stimulating factor (GMCSF), pegylated G-CSF (pegfilgrastim), interleukin-11, interleukin-3, and erythropoietin have regenerative effects on pancytopenia." (PMID 40429945, 2025).
Peri-Implantitis (1 paper, 2021). An inflammatory process with loss of supporting bone in the tissues surrounding functioning DENTAL IMPLANTS. "Therefore, increased expression of IL-11 due to the effects of nanotitania may be associated with exacerbation of peri-implantitis and possibly carcinogenesis." (PMID 34360848, 2021). "Since IL-11 acts as an osteolytic factor, the increased expression of IL-11 due to the influence of nanotitania may be a cause of the accelerated progression of peri-implantitis." (PMID 34360848, 2021).
polyp (1 paper, 2023). A usually exophytic mass attached to the underlying tissue by a broad base or a thin stalk. "Moreover, GC suppresses pro-fibrotic cytokines related to polyp growth, such as IL-11, the basic fibroblast growth factor (b-FGF), and the vascular endothelial growth factor (VEGF), thus globally reducing the inflammatory load at the level of the nasal mucosa." (PMID 37108966, 2023).
proliferative diabetic retinopathy (1 paper, 2024). Advanced retinopathy due to diabetes mellitus characterized by the formation of new vessels in the retina. "In vitreous samples from proliferative diabetic retinopathy (PDR) patients, elevated levels of IL-11Rα, but not IL-11, were detected." (PMID 39294742, 2024).
psoriasis vulgaris (1 paper, 2025). Plaque psoriasis is the most common presentation of psoriasis. "Considering the anti-inflammatory properties of IL-11, a phase I open-label clinical trial investigated the efficacy of daily subcutaneous administration of recombinant human interleukin-11 (rhIL-11) in 12 patients diagnosed with psoriasis vulgaris." (PMID 40731810, 2025).
Rectal prolapse (1 paper, 2020). Protrusion of the rectal mucous membrane through the anus. "Surprisingly, expression of Il11 in SMCs was sufficient to induce severe colonic inflammation and rectal prolapse within 3 days, which was followed by early mortality in Il11SMC animals." (PMID 31917819, 2020).
relapsing-remitting MS (1 paper, 2023). "Later studies found that IL11 is increased in the blood and cerebrospinal fluid of patients with early stage MS symptoms and also in patients with relapsing-remitting MS, where blood levels, likely from IL11-secreting CD4+ cells, increased further during periods of clinical deterioration." (PMID 38054591, 2023).
schistosomiasis (1 paper, 2025). An infectious disease caused by parasitic trematodes of the genus Schistosoma that colonize human blood vessels and release eggs that can cause granulomatous reactions leading to acute (swimmer's itch or acute schistosomiasis syndrome) or chronic disease. "Cytokines like IL‐11 or IL‐13 are known to be master regulators of fibrosis, especially in schistosomiasis‐associated fibrogenesis." (PMID 40751475, 2025).
schizophrenia (1 paper, 2022). A major psychotic disorder characterized by abnormalities in the perception or expression of reality. "Among pro-inflammatory cytokines, the levels of interleukin (IL)-1α, IL-6, IL-11, IL-12A, IL-15, IL-17A, and granulocyte colony-stimulating factor (G-CSF) in tears were elevated in the schizophrenia group (all P < 0.01)." (PMID 35223927, 2022). "Among pro-inflammatory cytokines, the levels of interleukin (IL)-1α, IL-6, IL-11, IL-12A, IL-15, IL-17A, and granulocyte colony-stimulating factor (G-CSF) in tears were significantly higher in patients with schizophrenia than that in normal controls (all P < 0.01)." (PMID 35223927, 2022).
Splenomegaly (1 paper, 2023). Abnormal increased size of the spleen. "It has previously been reported that hyperactivation of STAT3 results in splenomegaly: here PEGIL11 treatment induced splenomegaly in both wild-type and Asc-/- mice, suggesting IL11-induced splenomegaly occurs via inflammasome-independent mechanisms." (PMID 37292200, 2023).
Stillbirth (1 paper, 2023). Death of the fetus in utero after at least 22 weeks of gestation. "In our previous study, IL11 treatment from E10-17 caused preterm birth, stillbirth and reduced postnatal growth." (PMID 37292200, 2023).
Thromboembolism (1 paper, 2025). The formation of a blood clot inside a blood vessel that subsequently travels through the blood stream from the site where it formed to another location in the body, generally leading to vascular occlusion at the distant site. "Recombinant human interleukin-11 (rhIL-11) had the lowest platelet transfusion rate but the highest incidence of adverse events, whereas avatrombopag had the lowest rate of adverse events and thromboembolism." (PMID 40766766, 2025).
thymic lymphoma (1 paper, 2022). "In fact, we previously reported that certain cytokines such as IL-1β, IL-12p40 and IL-11 were secreted from macrophages after irradiation as assessed with a mouse model in which nearly 100% of mice develop thymic lymphoma after four-fractionated irradiation." (PMID 35336821, 2022).
triple-negative breast carcinoma (1 paper, 2013). An invasive breast carcinoma which is negative for expression of estrogen receptor (ER), progesterone receptor (PR), and human epidermal growth factor receptor 2 (HER2). "The combination of RGD, MMP, and IL-11 agents may have a unique role in detecting molecular marker-negative tumors, such as triple negative breast cancer cells, since those agents are not targets on the tumor cell itself." (PMID 23331017, 2013).
type 2 thrombocytopenia (1 paper, 2013). "In several cell lines, PaCS development follows cell differentiation/activation by trophic factors and cytokines, such as GM-CSF and IL-4 for DCs, IL-2 and IL-15 for NK cells, or thrombopoietin, IL-6 and IL-11 for megakaryocytes in type 2 thrombocytopenia." (PMID 24358206, 2013).
uterine cancer (1 paper, 2019). Primary or metastatic malignant neoplasm involving the uterine corpus and/or the cervix. "Excitingly, my studies show that blocking IL-11 can promote healthy pregnancy; stop uterine cancer growth and spread; and importantly preserve the future fertility of these women." (PMID 31114706, 2019). "I also provided evidence for efficacy of a novel nonchemo-/radio-therapy and non-hormonal treatment for uterine cancer, by blocking IL-11 proteins of interest." (PMID 31114706, 2019).
vivax malaria (1 paper, 2020). "The observed rise in TPO and IL-11 levels in our cohort indicates that increased platelet production occurs during vivax malaria in response to the reduction in circulating platelet counts." (PMID 32687542, 2020).
ZIKV infection (1 paper, 2022). "The downregulation of inflammatory genes CCL18, CCL19, CXCL6, CXCL9, IL6R, IL11, IL24, and Integrin Subunit Beta 3 (ITGB3) with ZIKV infection may reflect placental immune tolerance." (PMID 35304593, 2022).
tumor (364 papers, 2007 to 2026). "IL‐11 has also been implicated in several other aspects of tumor biology, including, but not limited to, stimulation of angiogenesis, hypoxic conditions, and drug‐resistance." (PMID 40968783, 2026). "MiR-17 and miR-20 bind to 3′-UTR of IL-8 to inhibit the in the inhibition of tumor metastasis to the neighbouring cells whereas the expression of miR-124 prevents bone metastasis caused by IL-11." (PMID 38726321, 2024). "IL11/STAT3 signaling effects downstream cyclin, which reflected in this study is that Ki67+ tumor cells were reduced both in IL11-deficient and IL11 mutein-treated tumors." (PMID 37365574, 2023). "We then crossbred Apcmin/+ mice, a classical spontaneous tumor model, with Il11−/− mice, to generate Il11-deficient environment in Apcmin/+ mice." (PMID 37365574, 2023). "Recent studies have discovered an emerging role of IL11 in various colitis-associated cancers, suggesting that IL11 mainly promotes tumor cell survival and proliferation in regulating tumorigenesis." (PMID 37365574, 2023). "IF analysis of subcutaneous tumors showed increased CD8+ cell infiltration in Il11-deficient tumor environment." (PMID 37365574, 2023). "Immunohistochemistry staining showed less Ki-67+ proliferating cells in Il11-deficient tumor environment." (PMID 37365574, 2023). "Recently, there is accumulating evidence suggesting that IL11 is an important tumor-promoting cytokine that that has both diagnostic and prognostic value in patients with NSCLC." (PMID 35883698, 2022). "The findings that cancer-associated fibroblasts secrete IL11 to promote tumor growth and confer chemoresistance has also been observed in other cancers including gastric cancer." (PMID 35883698, 2022). "IL11, possibly secreted from subepithelial myofibroblasts or tumor-associated endothelial cells, signals through STAT3 and stimulates gastric tumor epithelium to release IL33." (PMID 34235145, 2021). "IL-11 is associated with the recruitment of fibroblasts, supporting tumor invasion, immune escape, and selection of malignant cancerous cells; increased IL-11 expression is correlated with worse clinical prognosis." (PMID 32973519, 2020). "This review showed that a large number of pro-inflammatory ILs (IL-1, IL-6, IL-8, IL-11, and others) generated by host immune cells and/or tumor cells are linked with tumor aggressiveness, as confirmed by numerous preclinical studies." (PMID 31847214, 2019). "Mechanistically, YTHDF2 inhibited STAT3 phosphorylation and tumor growth by degrading IL11 mRNA, which encodes the dominant IL-6 family cytokine that endows gastrointestinal cancers with proliferative and invasive capacity." (PMID 31735169, 2019). "Our preclinical data argue strongly for a tumor promoting role of a signaling axis emanating from IL-11-induced, tumor cell-derived IL-33 and the subsequent hierarchical activation cascade of mast cells and tumor-associated macrophages." (PMID 31227713, 2019). "This interaction causes the tumor cells to produce factors such as PTHrP and IL-11, resulting in further osteoclastogenesis and perpetuation of osteolytic disease." (PMID 28938572, 2017). "Meanwhile, our results suggested not only secretion of IL-11 by TGF-β-stimulated cancer-associated fibroblasts (CAFs) but also EBI3 derived from CRC cells triggers gp130/STAT3 signaling to promote tumor growth." (PMID 27247488, 2016). "IL-11 belongs to IL-6 cytokine family, which consisted of IL-6, IL-11, IL-27, IL-30, IL-31, oncostatin M, and others, and it can be secreted by cancer-associated fibroblasts, myeloid cells, and tumor cell itself." (PMID 25929737, 2015). "In the present study, dietary iron enhanced colonic IL-6/IL-11-Stat3 signaling and promoted colonic inflammation and tumor development in a DSS mouse model of inflammation-associated colorectal tumorigenesis." (PMID 24223168, 2013).